THBD (thrombomodulin)
Diseases named in the same sentence as THBD in open-access papers (continued):
Sharing a sentence is not in itself a finding about the gene and the disease.
systemic inflammatory response syndrome (3 papers, 2017 to 2020). SIRS is a serious condition related to systemic inflammation, organ dysfunction, and organ failure. "The aim of this study was to investigate the association of serum thrombomodulin level in different pediatric sepsis syndromes and evaluate the relationship with disease severity and mortality." (PMID 28771554, 2017). "The aim of this study was to investigate the association of serum thrombomodulin level in different pediatric sepsis syndromes, and to evaluate the relationship with disease severity and mortality." (PMID 28771554, 2017). "This study demonstrated that serum thrombomodulin level, a biomarker of endothelial injury, was increased in different pediatric sepsis syndromes and correlated with disease severity and mortality." (PMID 28771554, 2017). "Increased serum thrombomodulin levels have been reported in different sepsis syndromes and to be correlated with disease severity." (PMID 28771554, 2017). "Increased serum thrombomodulin levels were found in different pediatric sepsis syndromes and correlated with disease severity and mortality." (PMID 28771554, 2017). "Increased serum thrombomodulin levels on days 1 and 3 of admission were found in different pediatric sepsis syndromes." (PMID 28771554, 2017). "In the current study, we found higher serum thrombomodulin levels on days 1 and 3 in the patients with different sepsis syndromes." (PMID 28771554, 2017). "This study is one of the few prospective, randomized, placebo-controlled studies to investigate the effects of human recombinant thrombomodulin, ART-123, in the treatment of DIC associated with infectious systemic inflammatory response syndrome (SIRS)." (PMID 31569648, 2019). "Recombinant human thrombomodulin (rTM) significantly decreases serum HMGB1 levels and improves systemic inflammatory response syndrome (SIRS) in patients with hematological malignancies." (PMID 32660524, 2020).
trauma (3 papers, 2021 to 2025). "Syndecan-1 is among the best-established markers of glycocalyx shedding, the plasma concentrations of the latter, as well as of heparan sulfate, chondroitin sulfate and soluble thrombomodulin are considerably elevated in trauma patients." (PMID 33740916, 2021). "The ISS is correlated with adrenaline, interleukin (IL)-6, histone-complexed DNA fragments, high-mobility group box 1 (HMGB1), soluble thrombomodulin (sTM) and protein C in trauma patients with high serum SDC-1 levels (≥ 63 ng/ml) but not in those with low SDC-1 levels (< 63 ng/ml)." (PMID 36237551, 2022).
type 2 diabetes (3 papers, 2016 to 2019). "The association between thrombomodulin and type 2 diabetes risk was assessed in one other study besides ours." (PMID 31783601, 2019). "Such factors as female sex, smoking habit, increased number of co-morbidities, higher BMI, and higher levels of LDL cholesterol and thrombomodulin increase the likelihood of depressive symptoms in elderly patients with type 2 diabetes." (PMID 26613755, 2016). "Female sex, smoking habit, increased number of co-morbidities, higher BMI, and higher levels of LDL cholesterol and thrombomodulin are the factors increasing the likelihood of having depressive symptoms in elderly patients with type 2 diabetes in multivariable model." (PMID 26613755, 2016).
age-related macular degeneration (2 papers, 2018 to 2019). Age-related loss of vision in the central portion of the retina (macula), secondary to retinal degeneration. "In our patient we found two polymorphisms already known as pathogenic for C3GN in CFH (p.V62I in SCR1) and THBD (p.A473V) genes, as well as a polymorphism so far associated to age-related macular degeneration (AMD) in C3 (p.R102G)." (PMID 29592796, 2018). "Next generation sequencing (NGS) showed polymorphism in CFH (p.V62I in SCR1) and THBD (p.A473V) already known as pathogenic for C3GN, as well as a mutation in C3 (p.R102G) associated only with age-related macular degeneration (AMD) so far." (PMID 29592796, 2018).
aneurysm (2 papers, 2019 to 2023). Bulging or ballooning in an area of an artery secondary to arterial wall weakening. "It has been reported that, thrombomodulin (TM) signals were predominantly localized to macrophages and VSMCs in human aneurysm specimens." (PMID 31651935, 2019).
aortic aneurysm (2 papers, 2022). A ruptured aneurysm located in the wall of the proximal portion of the descending aorta proceeding from the arch of the aorta. "Numerous reports have described the efficacy of recombinant thrombomodulin for DIC complicated by aortic aneurysms." (PMID 35163216, 2022). "In a previous case report, recombinant thrombomodulin was useful for treating chronic DIC in a patient with dissecting aortic aneurysm." (PMID 35806918, 2022). "Because of the need for intravenous administration and the fact that long-term medication is not covered by public insurance in Japan, recombinant thrombomodulin is often used in the treatment of DIC complicated by aortic aneurysm r perioperative DIC control." (PMID 35163216, 2022).
arteriosclerosis (2 papers, 2018 to 2022). A vascular disorder characterized by thickening and hardening of the walls of the arteries. "In patients with existing atherosclerotic disease or children without soluble thrombomodulin was positively associated with future CHD events and arteriosclerosis progression, which may reflect the degree of associated inflammation and endothelial damage." (PMID 36140236, 2022).
bladder adenocarcinoma (2 papers, 2006 to 2016). "Thrombomodulin is a highly specific marker for bladder adenocarcinoma, but it is expressed in only 59% of these tumors." (PMID 27006847, 2016). "CK7, CK20, CDX2, thrombomodulin, and β-catenin can help distinguish primary bladder adenocarcinoma from colonic adenocarcinoma; PSA and PSAP can help distinguish primary bladder adenocarcinoma from prostate adenocarcinoma." (PMID 27006847, 2016). "59% of primary bladder adenocarcinomas demonstrated significant expression of membranous thrombomodulin compared to 0% of colonic adenocarcinomas." (PMID 17040576, 2006). "The available evidence suggests that an immunohistochemical panel of CK7, CK20, CDX2, beta-catenin, thrombomodulin and Villin may best distinguish primary bladder adenocarcinomas from metastases." (PMID 17040576, 2006). "IHC can be helpful, as bladder adenocarcinoma is positive for CK7, CK20, CDX2, and thrombomodulin and negative for nuclear β-catenin." (PMID 27006847, 2016).
colitis (2 papers, 2016 to 2025). Inflammation of the colon. "Future studies will be necessary to determine whether 1,25(OH)2D-induced expression of THBD is needed for 1,25(OH)2D3 mediated healing of the intestinal mucosa in colitis." (PMID 40535337, 2025). "Although these genes are not well studied in the context of intestinal biology, THBD was recently shown to stimulate the growth of mouse intestinal organoids and to enhance mucosal healing in the murine model of dextran sodium sulfate (DSS)-induced colitis." (PMID 40535337, 2025).
colonic adenocarcinoma (2 papers, 2006 to 2016). "By contrast, colonic adenocarcinoma, while positive for CK20 and CDX2, is negative for CK7 and positive for thrombomodulin and nuclear β-catenin." (PMID 27006847, 2016).
dengue (2 papers, 2013 to 2021). "Levels of TNF-α, thrombomodulin and VWF were significantly increased in the two dengue groups than in healthy controls, but similar between patients with and without bleedings." (PMID 23890510, 2013).
endometrial cancer (2 papers, 2024 to 2025). Primary or metastatic malignant neoplasm involving the endometrium (mucous membrane that lines the endometrial cavity). "Furthermore, findings from the same study indicate that miR-18a-5p negatively influences THBD expression, and that the oncogenic impact of miR-18a-5p on endometrial cancer cells is counteracted by the overexpression of THBD." (PMID 40332167, 2025). "Moreover, the observed hypermethylation in the THBD promoter region suggests that epigenetic silencing could further contribute to the downregulation of THBD expression, adding another layer of complexity to the regulation of this gene in endometrial cancer." (PMID 40332167, 2025).
epithelioid mesothelioma (2 papers, 2013 to 2015). "Ber-EP4 and CEA are expected to be negative in MPM, but the negativity for thrombomodulin was surprising, considering that the reported sensitivity and specificity of thrombomodulin in epithelioid mesothelioma range from 61% to over 80%." (PMID 25849448, 2015).
graft versus host disease (2 papers, 2019 to 2024). An immune system disorder that occurs after allogeneic hematopoietic stem cell transplant and is a reaction of donor immune cells against host tissues. "Taken together, this provides a possible rationale for recombinant thrombomodulin‐mediated alleviation of graft versus host disease (GVHD) in mouse models of haematopoietic stem cell transplantation." (PMID 31287944, 2019). "There have been reports suggesting that treatment options for TA-TMA include reduction or discontinuation of calcineurin inhibitors that exacerbate vascular endothelial damage, control of infection and graft-vs-host disease, and recombinant thrombomodulin and fresh frozen plasma infusion." (PMID 39247211, 2024).
hemorrhage (2 papers, 2022 to 2024). Loss of blood from the vascular compartment to the exterior or into nonvascular body space as a result of rupture or severance of the blood vessels. "Notably, compared to monoclonal anti-CD41 Ig, anti-NS1 Ig exhibited relatively lower potency in hemorrhage-related pathogenesis, such as the hemorrhage score, proinflammatory cytokine induction, and thrombomodulin release." (PMID 39409186, 2024). "Meanwhile, the transcription of several coagulation-related genes, including THBD and SERPINB2, is substantially upregulated by VP35-dependent CREB1 activation, which may contribute to EBOV-related hemorrhage." (PMID 35474062, 2022).
Hepatic fibrosis (2 papers, 2023 to 2025). The presence of excessive fibrous connective tissue in the liver. "Some studies suggest that it alleviates oxidative stress by increasing antioxidant enzyme activity, while other studies indicate that antagonizing THBD can alleviate liver fibrosis by clearing senescent cells." (PMID 39852384, 2025). "By inhibiting thrombomodulin (THBD) signaling, a key pathway in the fate of senescent cells by vorapaxar, it is possible to eliminate senescent cells during the hepatic fibrosis process and maintain liver homeostasis." (PMID 38203352, 2023).
hypothyroidism (2 papers, 2012 to 2019). Abnormally low levels of thyroid hormone. "Factor VII, TAFI antigen, and thrombomodulin levels were higher in patients with hypothyroidism than in healthy subjects in another study, causally suggesting increased cardiovascular mortality in hypothyroidism." (PMID 31549496, 2019).
ischemia (2 papers, 2021 to 2025). A hypoperfusion of the BLOOD through an organ or tissue caused by a PATHOLOGIC CONSTRICTION or obstruction of its BLOOD VESSELS, or an absence of BLOOD CIRCULATION. "This is achieved by decreasing tissue factor expression and increasing thrombomodulin activity, helping prevent microvascular thrombosis and ischemia." (PMID 41010954, 2025). "Meanwhile, systemic hypoperfusion may also be associated with prolonged coagulation times by affecting thrombin generation, thrombomodulin expression from ischemia-sensitive endothelia, altering hemostasis, and leading to hypocoagulability." (PMID 34362183, 2021).
kidney damage (2 papers, 2021 to 2023). "To study the factors that may induce an upregulation of glomerular thrombomodulin, we next stained for the ETAR, which mediates kidney damage induced by VEGF inhibition." (PMID 33707524, 2021).
liver dysfunction (2 papers, 2025 to 2026). "Thrombomodulin infusion in cirrhotic hepatectomized rats improved the survival rate by preventing intrasinusoidal fibrin deposition and liver dysfunction." (PMID 40551534, 2025). "Some studies in cirrhotic rats have shown that injection of activated protein C or soluble thrombomodulin after extended hepatectomy permitted to decrease the postoperative liver dysfunction, but no data currently exist in human." (PMID 40551534, 2025).
Miscarriage (2 papers, 2010 to 2017). A pregnancy that ends at a stage in which the fetus is incapable of surviving on its own, defined as the spontaneous loss of a fetus before the 22th week of pregnancy. "Reduced expression levels of thrombomodulin were found in recurrent miscarriage group compared to controls (1,82-fold reduction), that corresponds to a reduction of 45% (from control group ΔCt) of thrombomodulin expression in spontaneous miscarriage group respect the control group." (PMID 20051099, 2010). "With this background, we performed a prospective case-control study measuring the gene expression of thrombomodulin in placental tissues from spontaneous recurrent miscarriage and voluntary abortion by Real-Time quantitative PCR to elucidate the role of this factor on human miscarriage." (PMID 20051099, 2010). "Reduced expression levels of thrombomodulin were found in recurrent miscarriage group compared to controls (1.82-fold of reduction), that corresponds to a reduction of 45% (from control group Delta CT) of thrombomodulin expression in spontaneous miscarriage group respect the control groups." (PMID 20051099, 2010). "We thus hypothesise that the THBD-p.Trp153Gly mutation might perturb the interaction between THBD and HMGB1, thereby leading to local enhanced inflammation at the foetal-placental interface and contributing towards miscarriage aetiology." (PMID 29195508, 2017).
peritoneal mesothelioma (2 papers, 2013 to 2015). A benign or malignant mesothelial neoplasm that arises from the peritoneum. "Finally, the histological diagnosis of peritoneal mesothelioma was performed on the basis of a positive staining for keratin markers such as calretinin and thrombomodulin, as well as negative staining using markers for adenocarcinoma such as carcinoembrionic antigen (CEA), CA-125 and CK 5/6." (PMID 26253127, 2015).
prostate adenocarcinoma (2 papers, 2016 to 2021). "In descending order of importance to distinguish from prostate adenocarcinomas, genes for uroplakin II, S100P, GATA3 and thrombomodulin had high discriminant loadings (> 0.3)." (PMID 33762601, 2021).
serous carcinoma (2 papers, 2013 to 2025). "This inverse relationship between miR-18a-5p and THBD expression supports the existence of a potentially critical miR-18a-5p/THBD regulatory axis, which may drive tumor aggressiveness, particularly in the more malignant histological subtypes such as serous carcinoma." (PMID 40332167, 2025).
urothelial carcinoma (2 papers, 2016 to 2021). A malignant neoplasm derived from the transitional epithelium of the urinary tract (urinary bladder, ureter, urethra, or renal pelvis). "Standard discriminant analysis of this study demonstrated that, in descending order of importance for the urothelial lineage markers, UKP2, S100P, GATA3 and THBD were the most important predictors for urothelial carcinoma by gene expression." (PMID 33762601, 2021). "Additionally, they consider that high–molecular weight cytokeratin and P63 are more sensitive for the diagnosis of urothelial carcinoma compared with thrombomodulin and S100P." (PMID 27256178, 2016). "The immunohistochemical study in our cases was consistent with a diagnosis of urothelial carcinoma when it turned out negative to PSA and positive to high molecular weight keratin (34BetaE12) and thrombomodulin." (PMID 27256178, 2016).
Varicose veins (2 papers, 2014 to 2019). Enlarged and tortuous veins. "Knowing that thrombomodulin can also have a role in proliferation, they also investigated a potential link for thrombomodulin genetic mutations in patients with varicose veins." (PMID 25520775, 2014). "Other studies have discovered associations between development of varicose veins and mutations of TIE2, NOTCH3, thrombomodulin, and transforming growth factor beta receptor, suggesting a genetic component in venous disease associated with PVC." (PMID 31921319, 2019).
abortion (1 paper, 2010). the ending of pregnancy by removing a fetus or embryo before it can survive outside the uterus. "We evaluate the Thrombomodulin expression in placental tissue from spontaneous recurrent miscarriage and voluntary abortion as controls." (PMID 20051099, 2010). "In this work we found a reduced expression of Thrombomodulin in placental tissue of women who experienced spontaneous recurrent abortion by Real-Time quantitative PCR." (PMID 20051099, 2010).
acute liver failure (1 paper, 2020). Rapid deterioration of liver function causing encephalopathy and coagulopathy. "The administration of recombinant human soluble thrombomodulin (rhsTM) significantly improves liver inflammation and increases the survival rate of patients with acute liver failure (ALF)." (PMID 32015385, 2020).
Arthritis (1 paper, 2021). Inflammation of a joint. "The lectin-like domain of thrombomodulin interferes with complement activation and protects against arthritis in mouse model." (PMID 33925132, 2021).
astrocytomas (1 paper, 2014). "Other proteins overexpressed in astrocytomas have also been implicated in tumor growth and invasion, such as the inter-cellular adhesion molecule 1 (ICAM-1), the neural cell adhesion molecule NCAM1 and the thrombomodulin (THBD)." (PMID 25360666, 2014).
babesiosis (1 paper, 2022). Babesiosis refers to a condition caused by microscopic parasites that infect the red blood cells. "Its level is also significantly correlated with the presence of markers of vascular endothelium dysfunction, such as thrombomodulin, which was found to be increased in dogs with babesiosis, as well as other markers of endothelium activation." (PMID 35163517, 2022).
bacterial sepsis (1 paper, 2009). "Activation of protein C is initiated by binding of thrombomodulin and decreased activation of protein C in bacterial sepsis has been shown to relate to downregulation of thrombomodulin." (PMID 19450727, 2009).
bladder tumours (1 paper, 2020). "In this study, loss of expression or reduced thrombomodulin was observed within bladder tumour cells compared to normal bladder cells." (PMID 33238953, 2020). "In terms of Bladder specific research however, our research provides new information on Thrombomodulin staining patterns in bladder tumours." (PMID 33238953, 2020). "There was significantly increased expression of CD31 (p < 0.001), HER-2 (p = 0.032), S100P (p < 0.001), COX-2 (p < 0.001), VEGFR-3 (p < 0.001) and decreased expression of thrombomodulin (p = 0.010) and CEACAM-1 (p < 0.001) in bladder tumours compared to normal bladder tissues." (PMID 33238953, 2020).
bladder urothelial carcinoma (1 paper, 2021). "In descending order of importance for the urothelial lineage gene expressions, UKP2, S100P, GATA3 and THBD were the most important predictors for bladder urothelial carcinoma based on the discriminant loading > 0.3." (PMID 33762601, 2021).
carotid atherosclerosis (1 paper, 2020). A thickening and loss of elasticity of the walls of carotid arteries that occur with formation of atherosclerotic plaques. "The association between high levels of soluble thrombomodulin and carotid atherosclerosis is in line with findings in Western populations." (PMID 32642566, 2020). "There is an association between high levels of soluble thrombomodulin and carotid atherosclerosis in Malawian adults." (PMID 32642566, 2020). "•High levels of soluble thrombomodulin are associated with carotid atherosclerosis." (PMID 32642566, 2020).
Cognitive impairment (1 paper, 2025). Abnormal cognition is characterized by deficits in thinking, reasoning, or remembering. "Soluble thrombomodulin is a promising biomarker for cognitive impairment in survivors of iTTP, and it is worthy of additional study." (PMID 39941363, 2025).